SOX4 (SRY-box transcription factor 4)
Diseases named in the same sentence as SOX4 in open-access papers (continued):
Sharing a sentence is not in itself a finding about the gene and the disease.
renal carcinoma (5 papers, 2017 to 2025). A carcinoma arising from the epithelium of the renal parenchyma or the renal pelvis. "The HIF1A-AS2-miR-30a-5p-SOX4 axis was associated with the malignant progression and development of renal carcinoma." (PMID 33710813, 2021). "The results showed that HIF1A-AS2 sponged miR-30a-5p to closely regulate SOX4 expression, and subsequently accelerated the malignant phenotypes of renal carcinoma cells and Wnt/β-catenin signaling, acting as an oncogene in the pathogenic mechanism of kidney carcinomas." (PMID 33710813, 2021). "Overexpression of HIF1A-AS2 reduced the relative expression of miR-30a-5p and subsequently increased the relative protein expression of SOX4 at the post-transcriptional level in renal cancer cells." (PMID 33710813, 2021). "lncRNA HIF1A-AS2 was found to be connected with the malignant development and progression of renal carcinoma through the HIF1A-AS2-miR-30a-5p-SOX4 axis." (PMID 34512816, 2021). "In conclusion, the results showed that the HIF1A-AS2-miR-30a-5p-SOX4 axis played significant roles in the progression and development of renal carcinomas." (PMID 33710813, 2021). "Together, our results showed that HIF1A-AS2 closely regulated SOX4 expression via sponging miR-30a-5p in renal carcinoma cells." (PMID 33710813, 2021). "The miR-30a-5p directly targeted SOX4 to reduce the relative protein expression levels of SOX4 in renal carcinomas." (PMID 33710813, 2021). "Together, our results indicated that HIF1A-AS2 accelerated malignant renal carcinoma cell phenotypes in a SOX4-dependent manner." (PMID 33710813, 2021). "The relative expression of HIF1A-AS2 was negatively correlated with the expression of miR-30a-5p, and was closely correlated with SOX4 mRNA levels in renal cancers." (PMID 33710813, 2021). "The CCK-8 assay results showed that pcDNA3.1-HIF1A-AS2 co-transfected si-NC accelerated renal carcinoma cell proliferation, and si-SOX4 co-transfected si-NC was reversed (P < 0.01) in 786-O and OS-RC-2 cells." (PMID 33710813, 2021). "HIF1A-AS2 acted as a microRNA sponge that actively regulated the relative expression of SOX4 in sponging miR-30a-5p and subsequently increased the malignant phenotypes of renal carcinomas." (PMID 33710813, 2021). "Si-SOX4 partially reversed the stimulatory effects on renal carcinoma cell proliferation induced by pcDNA3.1-HIF1A-AS2." (PMID 33710813, 2021). "The HIF1A-AS2-miR-30a-5p-SOX4 axis was involved in the progression of renal carcinomas, which highlights its possible application in clinical diagnosis and therapy." (PMID 33710813, 2021). "Silencing of SOX4 reversed the malignant renal carcinoma cell phenotype promoted by overexpressed HIF1A-AS2." (PMID 33710813, 2021). "Our study showed that the relative expression of HIF1A-AS2 was closely related to SOX4 expression, and that downregulated HIF1A-AS2 reduced SOX4 expression in renal carcinomas cells." (PMID 33710813, 2021). "Further experiments showed that the knockdown of SOX4 dramatically reversed the promotion of SOX4 expression induced by overexpressing HIF1A-AS2 in renal carcinoma cells." (PMID 33710813, 2021). "Our studies suggested that overexpression of miR-30a-5p reduced SOX4 expression and miR-30a-5p inhibition upregulated SOX4 expression in renal carcinomas cells." (PMID 33710813, 2021). "Moreover, si-SOX4 partially reversed the stimulatory effects on renal carcinoma cell migration induced by pcDNA3.1-HIF1A-AS2 and decreased by 97.08% in 786-O cells and 91.12% in OS-RC-2 cells." (PMID 33710813, 2021). "We wished to confirm whether HIF1A-AS2 regulated malignant phenotypes in a SOX4-dependent manner in renal carcinomas cells." (PMID 33710813, 2021). "Moreover, knockdown of SOX4 reversed the promotion of renal carcinoma cell proliferation induced by overexpression of HIF1A-AS2." (PMID 33710813, 2021). "Further experiments confirmed that decreasing SOX4 could alter WNT signaling in renal carcinomas cells." (PMID 33710813, 2021).
renal carcinoma (continued). "We confirmed whether HIF1A-AS2 regulated SOX4 expression in a miR-30a-5p-dependent manner in renal carcinoma cells." (PMID 33710813, 2021). "In addition, SOX4 knockdown reversed renal carcinoma cell apoptosis suppression induced by overexpression of HIF1A-AS2." (PMID 33710813, 2021). "Furthermore, si-SOX4 partially reversed the repression of apoptosis in renal carcinoma cells induced by pcDNA3.1-HIF1A-AS2 and increased by 93.60% in 786-O cells and 99.59% in OS-RC-2 cells." (PMID 33710813, 2021). "Furthermore, SOX4 knockdown reversed renal carcinoma cell migration induced by overexpression of HIF1A-AS2." (PMID 33710813, 2021). "Moreover, si-SOX4 partially reversed its stimulatory effects on renal carcinoma cells, and the quantity of Edu positive cells induced by pcDNA3.1-HIF1A-AS2 decreased by 104.5% in 786-O cells and 78.93% in OS-RC-2 cells." (PMID 33710813, 2021). "We found that LV-HIF1A-AS2 downregulated SOX4, β-catenin, Met, C-myc, cyclinD1, Fra-1, VEGF, and the expression of kidney carcinoma cells in vivo." (PMID 33710813, 2021). "HIF1A-AS2 was significantly upregulated in renal carcinoma cells and HIF1A-AS2 sponged miR-30a-5p to closely regulate SOX4 expression." (PMID 33710813, 2021). "Knockdown of SOX4 decreased MET, C-myc, cyclinD1, Fra-1, VEGF, and β-catenin expressions in renal carcinomas cells." (PMID 33710813, 2021). "Overexpression of HIF1A-AS2 increased SOX4, MET, C-myc, cyclinD1, Fra-1, VEGF, and β-catenin expressions in renal cells; knockdown of HIF1A-AS2 decreased SOX4, MET, C-myc, cyclinD1, Fra-1, VEGF, and β-catenin expression in renal carcinomas cells." (PMID 33710813, 2021).
small cell lung carcinoma (5 papers, 2007 to 2021). Small cell lung cancer (SCLC) is a highly aggressive malignant neoplasm, accounting for 10-15% of lung cancer cases, characterized byrapid growth, and early metastasis. "Thus, SOX1, SOX2, SOX3 and SOX21 as well as SOX4 were demonstrated to elicit humoral immune responses in small cell lung cancer patients." (PMID 17375044, 2007).
acute leukemia (4 papers, 2006 to 2023). A clonal (malignant) hematopoietic disorder with an acute onset, affecting the bone marrow and the peripheral blood. "We could also identify genes linked to malignant transformation of hematopoietic cells and one such example is Sox4, which was recently shown to cause acute leukemia if over-expressed in HSCs." (PMID 16600034, 2006). "SOX4 is thought to function as an oncogene in acute leukemia, particularly in the myeloid lineage." (PMID 28724437, 2017). "Apart from SOX4, BACH2 also holds important implications for human acute leukemia as it represents one of the few conserved upregulated genes in myeloid and lymphoid disease." (PMID 36517672, 2023). "Previous study has found that SOX4 expression is upregulated by a lncRNA CASC15 and promotes cell proliferation in acute leukemia." (PMID 32090981, 2020).
acute promyelocytic leukemia (4 papers, 2014 to 2022). An aggressive form of acute myeloid leukemia (AML), characterized by arrest of leukocyte differentiation at the promyelocyte stage, due to a specific chromosomal translocation t(15;17) in myeloid cells. "Recently, by crossing PML-RARA transgenic mice with BXH-2 mice, Kogan’s group has identified a new cooperating pathway to leukemogenesis: Sox4 overexpression accelerated PML-RARα initiated acute promyelocytic leukemia with increased penetrance and reduced latency of disease." (PMID 25314317, 2014).
Arthritis (4 papers, 2021 to 2023). Inflammation of a joint. "From analyzing the currently available data, SOX4 seems to be a potential diagnostic biomarker and therapeutic target of arthritis." (PMID 36835620, 2023). "However, SOX4 appears to be a potential diagnostic biomarker and therapeutic target of arthritis." (PMID 36835620, 2023). "In a similar mechanism, SOX4 was recently shown to be involved in promoting arthritis and in regulating FLS activities under both normal and inflammatory conditions." (PMID 36835620, 2023). "During this process an axis between TNF and SOX4 protein has been suggested, where SOX4 works as pivotal mediator and target of these cytokines to enable arthritis progression." (PMID 36835620, 2023). "This function of SOX4 during arthritis seems to be similar to its role in cancer, where it promotes metastasis and epithelial mesenchymal transition." (PMID 36835620, 2023). "Together these data reflect the pivotal role of SOXC TFs, especially SOX4, in regulating FLS and ELS actions under the in vivo inflammatory conditions associated with arthritis." (PMID 36835620, 2023). "Through direct and indirect binding to SOX4 TF, several upstream factors and signaling molecules have been recently reported to target SOX4 during arthritis, such as ROS)/TGF, TNF, SMOC2, AGEs, Lnc PART1, and the miRNA, miR-31." (PMID 36835620, 2023). "Mechanistically, SOX4 promoting arthritis has been documented to occur through regulating several signaling pathways." (PMID 36835620, 2023). "In addition, we have indicated that the natural flavonoid biomolecule pinocembrin can virtually interact with SOX4 and reduces its level expression in RA mouse models leading to a reduction in arthritis symptoms." (PMID 36835620, 2023). "Consistent with our findings, previous studies have shown that SOX4 is a critical transcription factor involved in the progression of multiple cancers, and it has also been found to be upregulated in mouse arthritis models and CD4 + T cells in the inflamed joints of RA patients." (PMID 36513634, 2022). "Thus, SOX4 appears to regulate the level of these enzymes and then promote arthritis." (PMID 36835620, 2023). "Their interdependent activities play a pivotal role in the transformation of FLS in arthritis and in the inflammatory pathology of diverse tissues where RELA and SOX4 are co-expressed." (PMID 35529852, 2022). "On the other hand, information about the epigenetic regulation of SOX4 during arthritis is not yet available." (PMID 36835620, 2023). "The functionally redundant activities of Sox4, Sox11 and Sox12 in TNF-induced arthritis and the diverse range of stimuli that can potentially activate the canonical NF-κB signaling in the FLS are suggestive of a role for multiple additional co-factors besides SOXC and RELA." (PMID 35529852, 2022). "Moreover, higher levels of SOX4 and SOX11 were found in the inflamed synovium of patients with arthritis." (PMID 34124371, 2021). "In addition, SOX4 was elevated in inflamed arthritis patients’ synovium compared to non-inflamed synovium and then was considered to be an early diagnostic biomarker during OA pathogenesis." (PMID 36835620, 2023).
endometriosis (4 papers, 2014 to 2025). The growth of functional endometrial tissue in anatomic sites outside the uterine body. "Transcription factor SOX4 was increased in peritoneum adjacent to endometriosis lesions." (PMID 25207642, 2014). "We next analyzed the expression levels of SOX4, PGR, FOXO1, HERC4, IGFBP1, and PRL in the mid-secretory endometrium of healthy women (control, n = 12) versus women who suffered RIF due to endometriosis (EMS-RIF, n = 12)." (PMID 35244538, 2022). "SOX4 is reported to have impacts on inhibition of apoptosis, increased cell proliferation and EMT, although a role for SOX4 has not been described in the context of endometriosis." (PMID 25207642, 2014).
gallbladder cancer (4 papers, 2012 to 2020). "SOX4, as a member of the SRY-related HMG-box (SOX) transcription factor family, has been demonstrated to be involved in tumorigenesis of many human malignancies; however, its role in primary gallbladder carcinoma (PGC) is still largely unknown." (PMID 22510499, 2012).
liver fibrosis (4 papers, 2020 to 2024). "SOX4, LGALS3, and SERPINE2 were strongly correlated with liver fibrosis grade and liver disease progression, with correlation coefficients (R) as high as 0.62 and 0.84 for SOX4 and 0.54 and 0.73 for LGALS3, respectively." (PMID 39194690, 2024). "Based on our analyses on a publicly available transcriptome database, we found that SOX4 was upregulated in LSECs from different liver fibrosis models." (PMID 39194690, 2024). "Among the corresponding transcription factors, GATA6, SOX4, and SOX9 have been reported to be associated with liver fibrosis." (PMID 32442221, 2020). "Moreover, we identified five key regulatory genes for endothelial dysfunction in liver fibrosis LSECs: SOX4, LGALS3, SERPINE2, CD52, and LPXN." (PMID 39194690, 2024). "This study, focusing on LSECs and the molecular bases of endothelial dysfunction during liver fibrosis from different mice models, found that SOX4, LGALS3, SERPINE2, CD52, and LPXN are potential key genes associated with endothelial dysfunction in liver fibrosis." (PMID 39194690, 2024). "Whether the upregulated expression of SOX4 in liver fibrosis LSECs is related to LSEC capillarization or the disappearance of fenestrae and the formation of basement membrane as well as its specific regulatory mechanisms still need further investigations." (PMID 39194690, 2024). "Subsequently, we conducted qRT-PCR analysis to examine the expression of five key genes (SOX4, LGALS3, SERPINE2, CD52, and LPXN) in the liver tissues of mice with liver fibrosis." (PMID 39194690, 2024). "This study identified key regulatory genes for endothelial dysfunction in liver fibrosis, namely SOX4, LGALS3, SERPINE2, CD52, and LPXN, which will provide new targets for the development of therapeutic strategies targeting endothelial dysfunction in LSECs and liver fibrosis." (PMID 39194690, 2024). "Therefore, SOX4, LGALS3, SERPINE2, CD52, and LPXN may serve as key regulatory genes for endothelial dysfunction in liver fibrosis LSECs." (PMID 39194690, 2024). "However, until now, there has been no report indicating a linkage of SOX4 with liver fibrosis." (PMID 39194690, 2024).
lymph node metastasis (4 papers, 2015 to 2022). "SOX4 protein level was significantly associated with lymph node metastasis (P = 0.001) and advanced tumor stages (stages III-IV; P = 0.003)." (PMID 28133610, 2017). "In our research, SOX4 expression level was also associated with clinical stage and lymph node metastasis of NPC and correlated with patients' overall survival time." (PMID 26578818, 2015). "Besides, SOX4 expression level was also associated with clinical stages and lymph node metastasis (P < 0.05)." (PMID 26578818, 2015). "Tumours in patients with higher expressions of SOX4 tended to be more invasive and were more likely to develop lymph node metastasis." (PMID 35522942, 2022). "We found overexpression of SOX4 was correlated with clinical stages, lymph node metastasis, and Ki-67 expression in NPC (P < 0.05)." (PMID 26578818, 2015). "Notably, six NPC patients with lymph node metastasis harbored SOX4 amplifications, which is involved in the Wnt signaling pathway and consistent with a previous study, demonstrating that SOX4 amplification was associated with lymph node metastasis and highly enriched in advanced‐stage NPC." (PMID 30950204, 2019).
lymphoma (4 papers, 2013 to 2025). A malignant (clonal) proliferation of B- lymphocytes or T- lymphocytes which involves the lymph nodes, bone marrow and/or extranodal sites. "Furthermore, transcriptional profiling across various lymphoma subtypes identified SOX4 as a molecular marker that is almost exclusively associated with CLL, reinforcing its specificity in disease biology." (PMID 40613823, 2025). "SOX4 expression in the nucleus of lymphoma cells was considered to be a positive result." (PMID 33923245, 2021). "Indeed, herein, downregulation of SOX4 was shown associated with upregulation of MIR129 upon either hypomethylating treatment or overexpression in GRANTA-519 and JEKO-1 lymphoma cell lines." (PMID 23406679, 2013). "Recently, a transcription factor gene, SRY-box transcription factor 4 (SOX4), and the cyclin-dependent kinase inhibitor 2A (CDKN2A), have attracted the attention of researchers as they may play essential roles in lymphoma oncogenesis." (PMID 33923245, 2021).
renal cell carcinoma (4 papers, 2016 to 2023). "In renal cell carcinoma, hsa-miR-204 directly targeted SOX4 to inhibit cell proliferation, migration, and invasion." (PMID 27253583, 2016). "Upregulated SOX4 by UCA1 contributes to proliferation and invasion in renal cell carcinoma." (PMID 30922402, 2019).
rheumatoid arthritis (4 papers, 2018 to 2023). A chronic, systemic autoimmune disorder characterized by inflammation in the synovial membranes and articular surfaces. "SOX-4–mediated CXCL13 production by CD4 T cells is involved in the formation of ectopic lymphoid-like structures (TLSs) in rheumatoid arthritis." (PMID 33332284, 2021). "Here the authors show that a transcription factor, Sox4, induces the expression of CXCL13 in CD4 T cells in vitro, and is associated with ELS formation in patients with rheumatoid arthritis." (PMID 30232328, 2018). "At the functional level, the SOX4-RELA genes were predicted to regulate pain signaling pathways, xenobiotic stress and tryptophan metabolism, nitric oxide signaling as well as macrophage, fibroblasts, and endothelial cell activities in rheumatoid arthritis." (PMID 35529852, 2022). "In vivo, Sox4 is significantly upregulated in synovial CD4+ T cells, when compared with blood CD4+ T cells, from patients with rheumatoid arthritis (RA), and further correlates with ELS formation in RA synovium." (PMID 30232328, 2018).
B-cell lymphomas (3 papers, 2012 to 2025). "Through the detection of markers like Myb and Sox4,93, 94 and the calculation of CNVs, these three clusters with malignancy characteristics were identified as B‐cell lymphoma." (PMID 40887856, 2025). "The murine leukemia virus typically targeted SOX4, and stabilized the SOX4 message to produce B-cell lymphomas that displayed increased SOX4 message levels." (PMID 23285187, 2012).
developmental delay (3 papers, 2023 to 2024). "Whole exome sequencing led to the identification of the first heterozygous SOX4 mutations in 2019, when four de novo missense variants in the HMG box were reported in individuals with developmental delays and mild facial dysmorphism." (PMID 38397148, 2024).
esophageal tumor (3 papers, 2015 to 2023). "Clinically, compared to normal adjacent tissues, esophageal tumor samples showed an up-regulation of SOX4, EZH2, and HDAC3 in which the EZH2 expression was significantly increased in metastatic ESCC tissues." (PMID 34973135, 2023). "SOX4 promotes esophageal tumor cell proliferation and invasion by silencing miR-31 via the activation and stabilization of a co-repressor complex with EZH2 and HDAC3." (PMID 34973135, 2023). "Clinically, when compared to normal adjacent tissues, esophageal tumor samples show upregulation of SOX4, EZH2, and HDAC3, and EZH2 expression is significantly increased in metastatic ESCC tissues." (PMID 25644061, 2015). "Here, we report that SOX4 promotes esophageal tumor cell proliferation and invasion by silencing miR-31 via activation and stabilization of a co-repressor complex with EZH2 and HDAC3." (PMID 25644061, 2015). "Similarly, the suppressive effect of miR-31 on the SOX4 3′-UTR activity was observed in the esophageal tumor cell lines, TE8 and FLO1." (PMID 25644061, 2015).